INS (insulin)
Diseases named in the same sentence as INS in open-access papers (continued):
Sharing a sentence is not in itself a finding about the gene and the disease.
diabetes (continued). "In addition to significant differences in BMI, insulin treatment, and family history of diabetes, we observed a notable difference in weight (50.60 kg vs. 59.97 kg, P = 0.031), suggesting that body weight may be a potential indicator for distinguishing MDM from type 2 diabetes." (PMID 39749018, 2024). "The addition of a GLP-1RA to metformin, as opposed to metformin alone or metformin plus insulin, improved lung function (FEV1 and FVC) in a prospective cohort of 32 patients with diabetes who did not have obstructive lung disease." (PMID 38398039, 2024). "Additionally, the effectiveness of vitamin D supplementation may vary depending on health status (diabetic or non-diabetic), diabetes type (type 1 or type 2), and other outcome variables (e.g., diabetes prevalence, blood glucose concentration, and insulin level)." (PMID 39339785, 2024). "The analgesic effects of insulin and its disorders in STZ‐induced short‐term diabetes demonstrated that diabetes (absence of peripheral insulin) increases pain sensation." (PMID 38639646, 2024). "Diabetes is known to induce damage to the liver and kidney, but no alterations were observed in these organs in TTA-DFP-nCOF/insulin-treated rats, demonstrating that the particles are harmless." (PMID 38167129, 2024). "This systematic review and meta-analysis allow us to conclude that combined exercise training can be an effective strategy to improve some glucose metabolism markers, such as fasting glucose, insulin, and HOMA-IR in sedentary adults without diabetes." (PMID 38253590, 2024). "These ICI-induced diabetes patients also require complex insulin therapy with no possibility of de-escalating insulin treatment, as remission of ICI-induced diabetes is very unlikely." (PMID 39006601, 2024). "Only ten participants were previously diagnosed with type 2 diabetes and not on insulin at the time of their DKA admission, so we excluded them from further analysis, and only focused on the 88 participants with newly diagnosed diabetes." (PMID 38240751, 2024). "In patients with HF and DM, however, glycaemic control and type of diabetes treatment emerged as significant confounders of the obesity paradox, with no benefit from high BMI in patients with insulin treatment or poor glycaemic control." (PMID 37608126, 2024). "In a prospective study on HNF1A-diabetes (n = 27) and HNF4A-diabetes (n = 7) not on SU at diagnosis, 25 of the 31 patients on insulin discontinued insulin but only 12 (48%) achieved an HbA1c of 7.5%23." (PMID 39025920, 2024). "DKA is one of the most serious acute metabolic complications of diabetes mellitus (DM), and the main mechanism of DKA is a lack of insulin in the body." (PMID 38225984, 2024). "While 123mAb selectively deleted insulin-reactive B cells in VH125Tg/NOD mice, it only prevented diabetes in female NOD but not VH125Tg/NOD mice (male mice were not evaluated)." (PMID 38515750, 2024). "Even though AVP induces insulin secretion, using high concentrations of AVP to treat diabetes is not advisable due to its many receptors and functions." (PMID 39217353, 2024). "Next, to explore the protection of MSCs-Exo in DKD, we injected MSCs-Exo and insulin into DKD mice, and db/m mice without diabetes were used as normal controls." (PMID 39039856, 2024). "The National Diabetes Audit (NDA) has identified over 90,000 who meet these criteria but who are not using an insulin pump." (PMID 38504346, 2024). "Diabetes mellitus (DM) is a persistent and currently untreatable metabolic disease resulting from either a complete lack of insulin (Type 1 Diabetes Mellitus, T1DM) or a partial lack of and/or an insufficient effect of insulin (Type 2 Diabetes Mellitus, T2DM)." (PMID 39335656, 2024). "The combination of GLP-1RA with metformin, in contrast to metformin alone or metformin plus insulin, improved lung function (FEV1, FVC) in a prospective cohort of 32 patients with diabetes who did not have lung disease." (PMID 39272654, 2024).
diabetes (continued). "They compared 31 term infants of mothers with diet controlled GDM (diet-GDM group), 16 infants of mothers with insulin controlled GDM (insulin-GDM group), and 55 term infants whose mothers did not have diabetes (control group)." (PMID 39315360, 2024). "In cases without diabetes (n = 22) a significant correlation was observed between the HOMA-R (r = -0.586, p = 0.004) and the fasting insulin levels (r = -0.650, p = 0.001) on the one hand and the serum SHBG levels on the other." (PMID 39014506, 2024). "Type 1 diabetes mellitus (T1DM) is characterized by an absence or near-absence of β-cell function, necessitating insulin therapy for survival." (PMID 39065795, 2024). "Although both mushrooms and fenugreek do not affect insulin secretion or synthesis, our research shows that mushrooms can improve the TAS of diabetes model rats." (PMID 39885962, 2024). "The patient tested negative for typical type 1 diabetes mellitus (T1DM) autoantibodies including glutamic acid decarboxylase antibodies (anti-GAD), insulin autoantibodies (anti-insulin), and anti-islet cell antibodies (anti-ICA)." (PMID 39450164, 2024). "Irrespective of diabetes status, IGPTT demonstrated a decrease in insulin sensitivity in the obese (OND and OD) groups." (PMID 39474247, 2024). "Furthermore, this pancreatic reclaim of its insulin synthesis capability and secretagogue might be a result of the presence of immature β-cells that evaded the destructive actions of the single dose of STZ administered to induce diabetes and later became mature or activated by GE treatment." (PMID 38785837, 2024). "In conclusion topical insulin represents a safe and effective therapeutic option for PED treatment in patients with or without diabetes." (PMID 38816428, 2024). "No cases were reported in liver-transplanted individuals with diabetes receiving SGLT2 inhibitors, insulin or metformin, neither in kidney or lung-transplanted patients treated with GLP1RAs." (PMID 38779453, 2024). "Type 1 diabetes mellitus (T1DM) results from autoimmune β‐cell destruction in the pancreas, which leads to a complete lack of insulin production." (PMID 38279951, 2024). "Patients with diabetes who fulfilled STAMPEDE or DSS entry criteria had lower BMI, higher HbA1c levels, and were more likely to use insulin than those UCLA patients who would not have met these studies’ entry criteria." (PMID 38911638, 2024). "Type 1 diabetes mellitus (T1DM) is a disease in which the pancreas produces little or no insulin, whereas insulin resistance and insufficient insulin are the primary contributors to the development of type 2 diabetes mellitus (T2DM)." (PMID 38801705, 2024). "Regarding the level of knowledge about diabetes, measured by the DKT scale, both groups displayed a medium level of knowledge (59% for the non-insulin-treated and 62.5% for the insulin-treated)." (PMID 39791030, 2024). "In late-stage diabetes or when glycemic control is not achieved with non-insulin drugs, such as oral antidiabetics and GLP1-RA, the addition of or the switch to insulin therapy is recommended." (PMID 38610878, 2024). "During the previous studies, researches about PTP1B mainly focused on diabetes mellitus, because PTP1B is a negative insulin signaling pathway regulator; hence inhibiting PTP1B increases insulin sensitivity and effectively controls diabetes." (PMID 39517122, 2024). "In individuals with compromised insulin signaling, such as those with type 2 diabetes mellitus (T2DM), insulin fails to suppress hepatic gluconeogenesis, even in the fed state, critically influencing blood glucose regulation." (PMID 38632455, 2024). "We further investigated the clinical relevance by analyzing the expressions of Insulin, IRS1, IRS2, and NEDD8 in ovarian cancer tissues from patients with or without type 2 diabetes mellitus." (PMID 38272982, 2024).
diabetes (continued). "Finally, although high CV was related to the presence of diabetes mellitus, the lack of detailed information about insulin dosage, duration of diabetes, and other possible diabetes-related complications, which means that confounding related to diabetes mellitus may not have been fully addressed." (PMID 38467770, 2024). "Trialled in three people with T1D (pwT1D) and seven without diabetes, the system showed superiority compared with multiple daily injections (MDI) or ‘open‐loop’ insulin delivery." (PMID 39291355, 2024). "This approach resulted in an increase in insulin secretion without altering gene transcription in the cell itself, successfully reversing STZ-induced diabetes in mice over a prolonged period." (PMID 39279997, 2024). "Although patients who adhered to the recommendations had longer duration of diabetes and higher SBP, and were more likely to use insulin, the effect of these factors was no longer remained significant after applying multivariate regression analysis." (PMID 38877501, 2024). "Compared with the non-diabetic group, individuals with diabetes had higher age, BMI, SBP, INS, TG, UA, and UHR levels (p<0.001), and lower DBP, TC, LDL-C, HDL-C, Non-HDL-C levels (p<0.001)." (PMID 39916754, 2024). "Our results showed that combined aerobic and resistance exercise programs were effective in reducing fasting glucose, fasting insulin, and IR index (measured by HOMA-IR) in sedentary adults without diabetes." (PMID 38253590, 2024). "Patients with type 2 diabetes mellitus (T2DM) have no less insulin levels than healthy people, but their body is insensitive to insulin, leading to elevated blood sugar levels." (PMID 39076511, 2024). "There has been continuous progress in diabetes management over the last few decades, not least due to the widespread dissemination of continuous glucose monitoring (CGM) and automated insulin delivery systems." (PMID 38894740, 2024). "Based on Anatomical Therapeutic Chemical (ATC) codes we identified the following subgroups: persons without diabetes, persons using "non-insulin GLD only", "insulin and non-insulin GLD" and "insulin only"." (PMID 39385069, 2024). "Thus, many adults with diabetes diagnosed at the time of presenting with DKA (‘ketosis-onset diabetes’), especially those with an obese phenotype with acanthosis nigricans, and absence of anti-GAD antibodies, could potentially be weaned off insulin safely using a standardised protocol." (PMID 38240751, 2024). "Various Egyptian studies have emphasized diabetes epidemiology, but no study was conducted in Egypt regarding KAP in diabetic patients on insulin." (PMID 38594659, 2024). "Compared with multiple daily insulin injections (MDI), continuous subcutaneous insulin infusion (CSII) is significantly more expensive and has not been widely used in Chinese type 1 diabetes mellitus (T1DM) patients." (PMID 38872219, 2024). "In the subgroup of subjects with and without diabetes, not taking diabetic medications, by 6 months (weight nadir), the HOMA-IR values and fasting insulin significantly declined for RYGB (p = 0.02), GS (p < 0.0001) and for DIET (p = 0.01)." (PMID 37055514, 2023). "There are 2 main subtypes of diabetes: Type 1 Diabetes (T1DM), in which the pancreas is producing little or no insulin due to destruction of insulin-producing beta cells by autoimmune process." (PMID 37072577, 2023). "Though PMDT centres had enhanced resources for diabetes management, three participants at TB-DOTS facilities in Negros spoke about periods when insulin was not in stock." (PMID 37749519, 2023). "In Type 1 diabetes mellitus (T1DM), the endocrine pancreas fails to produce insulin in sufficient quantities, if at all." (PMID 37384782, 2023). "O304 rapidly reduced glucose levels without enhancing plasma insulin levels also in STZ mice where the treatment was initiated first at day 15, i.e., when the mice had developed overt diabetes." (PMID 37626210, 2023).
diabetes (continued). "Baicalin treatment reduced blood levels of non-esterified fatty acids (NEFAs) in insulin-resistant mice, rats on an HFD, and rats with diabetes induced by feeding an HFD/HSD and administration of STZ." (PMID 38203600, 2023). "A similar type of dysbiosis is shown in patients with diabetes and NASH, but not in those treated with insulin." (PMID 37852976, 2023). "Several studies have reported that polysaccharides from natural products may improve diabetes symptoms mainly through regulating the OS, inhibiting α-amylase and α-glucosidase, enhancing insulin secretion and improving glucose metabolism in a non-insulin-dependent manner." (PMID 37497112, 2023). "Diabetes-related distress (PAID) was similar in the GDM-Diet and GDM-Insulin groups at both time points and did not change significantly between the initial and subsequent measurement." (PMID 36733299, 2023). "Type 2 diabetes mellitus (T2DM) is characterized by insulin resistance and a relative lack of insulin secretion from pancreatic beta cells." (PMID 37100872, 2023). "An increased diabetes duration, increased HbA1c levels, increased use of insulin, and increased postural instability were found in individuals with DPN compared to individuals with diabetes without DPN." (PMID 38025708, 2023). "Diabetes-related distress was similar in the GDM-Diet and GDM-Insulin groups at both time points and did not change during pregnancy." (PMID 36733299, 2023). "In patients with or without diabetes in both surgical and medical ICU’s, The American College of Physicians (ACP) advocates against the use of intensive insulin therapy." (PMID 37120562, 2023). "Importantly, we could not find any statistical differences between children who had at least one positive ICA or GADA test and those who presented as all-negative with respect to blood glucose, hemoglobin A1c, insulin, and C-peptide levels at diagnosis—even in the presence of diabetes ketoacidosis." (PMID 36835954, 2023). "Type 2 diabetes mellitus (T2DM), also known as non-insulin-dependent diabetes or adult-onset diabetes, is characterized by insulin resistance and inadequate insulin secretion." (PMID 37759802, 2023). "Based on the presence or absence of insulin, diabetes mellitus can be classified into two primary groups: type 1 diabetes mellitus (T1DM) and type 2 diabetes mellitus (T2DM)." (PMID 38111457, 2023). "Basal insulin therapy and the accompanied fear of hypoglycemic events is known to negatively affect the HRQOL of non-transplant diabetes patients." (PMID 37600749, 2023). "Specifically, when applied to children and teenage patients diagnosed with type 1 diabetes mellitus (T1DM), CC demonstrates the potential for substantial improvements in metabolic control without any adverse effects on weight or increased insulin requirements." (PMID 38111457, 2023). "No cases of monogenic diabetes were found in the small subpopulations tested with diabetes diagnosed 12-24 months in three studies sequencing KCNJ11 and INS genes only (n = 58–70)." (PMID 37794142, 2023). "Regardless of the diabetes group, there was not any difference between metformin plus any other OAA and metformin plus insulin (p = 0.1478)." (PMID 36979709, 2023). "Diabetes is a chronic disease, and its T1DM version is characterized by the fact that the subject’s pancreas produces practically no insulin, which calls for a life-lasting treatment consisting in the daily administration of amounts of insulin." (PMID 36991668, 2023). "Type 1 diabetes mellitus (T1DM) manifests as the destruction of pancreatic islet function leading to an absolute lack of insulin secretion and production of specific insulin autoantibodies." (PMID 38173714, 2023). "As the most prevalent form of DM, T2DM, which is also known as non-insulin-dependent diabetes, is mainly caused by impaired insulin secretion by pancreatic beta cells and resistance of insulin-sensitive tissues to insulin action, resulting in a relative lack of insulin." (PMID 37111299, 2023).
diabetes (continued). "Consequently, this viral infection can lead to pancreatic damage and impaired insulin production, resulting in the emergence of hyperglycemia, even in individuals without pre-existing Diabetes Mellitus (DM)." (PMID 37649125, 2023). "The FPIR is physiologically followed by a second, delayed release of insulin in newly formed vesicles, which is represented by the biphasic insulin profile observed during an OGTT in an individual without diabetes." (PMID 37712956, 2023). "In agreement with this, one group recruited cohorts of individuals without diabetes, with prediabetes or with T2DM on insulin." (PMID 37029208, 2023). "The study also found that caffeine did not affect hippocampal metabolism or insulin signaling, as HFD did not induce diabetes nor impair hippocampal insulin signaling or metabolism in mice." (PMID 37371407, 2023). "Therefore, the assessment of C-peptide provides a mirror of the secretory pattern of insulin in healthy individuals as well as in people with diabetes mellitus (DM) of various subtypes regardless of insulin therapy." (PMID 37432211, 2023). "Considered individually, at baseline one woman had type 2 diabetes mellitus (T2DM) and was treated with insulin, while no other patient showed an alteration of glucose metabolism." (PMID 37305037, 2023). "Hiking tours such as the one organized for this study can improve quality of life/well-being without increasing diabetes distress and are considered relatively safe for T2DM patients, even for those being treated with insulin." (PMID 36674186, 2023). "In type 2 diabetes mellitus (T2DM), either the body does not produce sufficient insulin or it becomes resistant to insulin." (PMID 36770672, 2023). "Less than half of our participants were aware that insulin is safe during pregnancy, although this observation may be influenced by the large proportion of nulliparous women in the study who may not have received specialized diabetes treatment counseling during pregnancy." (PMID 37828526, 2023). "Two of the WESDR trial reports (904 participants) evaluated linear trends in the effect of diabetes duration on incidence of PDR in people with older‐onset T2D, which authors also subgrouped as requiring or not requiring insulin (WESDR: Klein 1989a and 1994b)." (PMID 36815723, 2023). "Another common inflammatory marker related to diabetes, CRP, has been suggested to be influenced by body fat composition rather than glucose control or insulin sensitivity." (PMID 37520541, 2023). "Lack of efficient insulin secretion from the pancreas can lead to impaired glucose tolerance (IGT), prediabetes, and diabetes." (PMID 37758822, 2023). "We report a patient with type 1 diabetes mellitus (T1DM), on hemodialysis, who presented with diabetic ketoacidosis (DKA) due to non-adherence to insulin." (PMID 37456416, 2023). "Administration of WJMSC-CM and insulin for 60 days did not significantly reduce the mRNA expression level of Bax in Dia + CM and Dia + INS in comparison to the untreated diabetes group." (PMID 37081849, 2023). "Importantly, we show for the first time that BCL-XL overexpression protects human β-cells without compromising insulin release, which sets the stage for the use of β-cell-specific BCL-XL overexpression as a potential therapeutic strategy in order to prevent β-cell loss during diabetes development." (PMID 36982731, 2023). "For the individual medication classes within “Drugs used in diabetes”, we found that during follow-up more persons in the SMI group redeemed insulin and analogues compared to the non-SMI group." (PMID 37310947, 2023). "Yet the National Diabetes Audit (NDA) demonstrates slow and unequal progress in uptake of insulin pumps; around 90,000 people who meet NICE criteria are not prescribed insulin pumps (NDA)." (PMID 37653413, 2023).